BAG1 (BAG cochaperone 1)
Description:
Co-chaperone for HSP70 and HSC70 chaperone proteins. Acts as a nucleotide-exchange factor (NEF) promoting the release of ADP from the HSP70 and HSC70 proteins thereby triggering client/substrate protein release. Nucleotide release is mediated via its binding to the nucleotide-binding domain (NBD) of HSPA8/HSC70 where as the substrate release is mediated via its binding to the substrate-binding domain (SBD) of HSPA8/HSC70. Inhibits the pro-apoptotic function of PPP1R15A, and has anti-apoptotic activity. Markedly increases the anti-cell death function of BCL2 induced by various stimuli. Involved in the STUB1-mediated proteasomal degradation of ESR1 in response to age-related circulating estradiol (17-beta-estradiol/E2) decline, thereby promotes neuronal apoptosis in response to ischemic reperfusion injury (By similarity).
Synonyms: BAG-1; HAP; RAP46
Tractability: Small molecule: a structure with a bound ligand is known. PROTAC: UniProt records ubiquitination sites on it; ubiquitination databases record sites on it; its protein half-life has been measured.
Gene: Protein-coding gene on chromosome 9 (33,247,820 to 33,264,720, reverse strand). Ensembl gene ENSG00000107262.
Subcellular location: Nucleus (Isoform 1); Cytoplasm; Cytoplasm (Isoform 2); Nucleus; Cytoplasm (Isoform 4)
Subcellular location (Human Protein Atlas): Nucleoplasm; Cytosol
Pathways (Reactome):
Cellular responses to stimuli: Regulation of HSF1-mediated heat shock response
Gene Ontology:
Molecular function: adenyl-nucleotide exchange factor activity; protein binding; ubiquitin protein ligase binding; protein-folding chaperone binding
Biological process: protein folding; cell surface receptor signaling pathway; negative regulation of apoptotic process; positive regulation of smooth muscle cell apoptotic process; protein stabilization
Cellular component: cytosol; nucleoplasm; nucleus; cytoplasm; membrane
Genetic constraint (gnomAD): Loss-of-function variants: 30 observed, 27.54 expected, observed/expected ratio (o/e) 1.09, 90% interval 0.81 to 1.48. The upper end of that interval is the gene's LOEUF score, 1.48, which puts it in group 6 of 6, group 1 being the genes least tolerant of losing a copy. Missense variants: 443 observed, 415.42 expected, observed/expected ratio (o/e) 1.07, 90% interval 0.99 to 1.15. Synonymous variants: 187 observed, 167.54 expected, observed/expected ratio (o/e) 1.12, 90% interval 0.99 to 1.26.
Homologues: Orthologues: chimpanzee BAG1 (98% identical), macaque BAG1 (95% identical), dog BAG1 (77% identical), pig BAG1 (74% identical), mouse Bag1 (72% identical), guinea pig BAG1 (68% identical), rat Bag1 (64% identical), zebrafish bag1 (35% identical), Caenorhabditis elegans bag-1 (14% identical).
Diseases named in the same sentence as BAG1 in open-access papers:
BAG1 is named in the same sentence as 88 diseases in open-access papers, as found by Europe PMC text mining. Sharing a sentence is not in itself a finding about the gene and the disease. The quoted sentences say what the papers report.
breast carcinoma (48 papers, 1999 to 2025). "Alternations in target miRNA expression due to directly or indirectly affected by Bag-1 deficiency provide novel results for the relationship between different Bag-1 expressions and miRNA profiles in breast cancer." (PMID 37533517, 2022). "BAG-1 (BAG family molecular chaperone regulator 1), a multifunctional protein that controls apoptosis, has recently been linked to better survival in women with early-stage breast cancer." (PMID 35887080, 2022). "The knockout of Bag-1 results in a significant increase in apoptotic neuronal cell populations, whereas high levels of Bag-1 causes chaperone-mediated long- term survival of breast cancer cells." (PMID 34995286, 2022). "Here, we discuss the differential expression profiles of miRNAs in Bag-1 deficiency leading to breast cancer progression in MCF-7 cells." (PMID 37533517, 2022). "Elevated protein levels of BAG-1 determined in metastatic cancer patients and associated with decreased drug-induced apoptosis in breast cancer." (PMID 37533517, 2022). "The current study aimed to screen the differential expressed miRNAs and determine the potential targeted genes and pathways in Bag-1 deficient conditions in MCF-7 breast cancer cells." (PMID 37533517, 2022). "It has been well implicated that increased Bag-1 expression is associated with breast cancer progression and invasion." (PMID 37533517, 2022). "Accordingly, we proposed that Bag-1 overexpression enhances the tumorigenic potential, whereas knockout of Bag-1 causes a mesenchymal phenotype for breast cancer cells." (PMID 34995286, 2022). "The multifunctional anti-apoptotic Bcl-2-associated athanogene (Bag-1) protein is overexpressed in multiple cancer types, including breast cancer, and is a potential drug target for cancer treatment." (PMID 31883527, 2019). "In this study, we investigated in detail the effects of Bag-1 on major cell survival pathways associated with breast cancer." (PMID 31883527, 2019). "The anti-apoptotic protein Bcl-2-associated athanogene-1 (BAG-1) is frequently increased in breast cancer and pre-invasive breast disease compared to normal breast epithelium." (PMID 28510570, 2017). "Bcl-2-associated athanogene 1 (Bag-1) is a multifunctional protein overexpressed in breast cancer and ductal carcinoma in situ." (PMID 27043661, 2016). "To identify an association between BAG-1 gene expression levels and patient outcome, we examined two published breast cancer gene expression data sets." (PMID 19066611, 2009). "Although numerous studies have shown that different expression levels of BAG-1 show different functions in breast cancer, miRNA profiles of Bag-1-deficient cells associated breast cancer development remains largely unknown." (PMID 37533517, 2022). "Thus, the positive association between high Bag-1 expression and cell survival mechanism in breast cancer cells is regarded as a potential predictive marker of the clinical outcome of breast cancer." (PMID 34995286, 2022). "Although previous studies have demonstrated miRNA-mediated breast cancer development, the miRNA expression profile in Bag-1 deficient-breast cancer cells is unknown." (PMID 37533517, 2022). "Increased levels of BAG-1 are associated with better breast cancer outcomes." (PMID 28510570, 2017). "As expression of BAG-1 protein is frequently increased in breast cancer, we examined whether an association might exist between BAG-1 mRNA levels and disease outcome." (PMID 26958811, 2016). "Furthermore, BAG-1 expression has been associated with the prognosis of a variety of human malignancies, such as breast cancer and lung cancer." (PMID 22567091, 2012). "In the whole cohort (n=276), high nuclear BAG-1 expression was associated with a favourable prognosis for all measures of outcome in univariate analysis: local recurrence (P=0.002), distant metastases (P<0.0001) and breast cancer-specific death (P<0.0001)." (PMID 19066611, 2009).
breast carcinoma (continued). "BAG-1 (bcl-2-associated athanogene) enhances oestrogen receptor (ER) function and may influence outcome and response to endocrine therapy in breast cancer." (PMID 19066611, 2009). "ZR-75-1 cells stably expressing mutated forms of Bag-1 display retarded growth in vivo and in vitro, suggesting that targeting Bag-1 might be a useful strategy for treating breast cancer." (PMID 18430249, 2008). "Investigating the interaction networks between Bcl‐2‐associated athanogene (Bag)‐1 and other chaperone proteins may further the current understanding of the regulation of protein homeostasis in breast cancer cells and contribute to the development of treatment options." (PMID 39049197, 2024). "This is further emphasized by studies in multiple breast cancer cell lines that have demonstrated differential response in growth to BAG-1 knockdown or KO." (PMID 38412481, 2024). "We demonstrated that Bag‐1 overexpression promoted HER2 expression in breast cancer cells, thereby resulting in the concurrent constitutive activation of the HSF1–HSP axis." (PMID 39049197, 2024). "MCF‐7 and BT‐474 breast cancer cells were transfected with Bag‐1 plasmid or Bag‐1 siRNA to assess the impact of Bag‐1 on cell survival, with cell viability monitored beyond a 72‐h period." (PMID 39049197, 2024). "A possibility exists that X15695 also disrupts interaction of BAG1 with ERα to account for its inhibitory action on E2 target gene expression in the ER+ breast cancer cells." (PMID 37520743, 2023). "In this study, we generated stable Bag-1 knockout (KO) MCF-7 breast cancer cells to monitor stress-mediated cellular alterations in comparison to wild type (wt) and Bag-1 overexpressing (Bag-1 OE) MCF-7 cells." (PMID 34995286, 2022). "Akt is located in a protein complex consisting of B-Raf, C-Raf, and Bag-1 in breast cancer cells, which leads to inhibition of apoptosis by the phosphorylation and relocalization of Bad to nucleus." (PMID 34995286, 2022). "The immunohistochemical studies showed that Bag-1 cytoplasmic positive staining scores were correlated with breast cancer progression in estrogen receptor-positive tissue samples." (PMID 37533517, 2022). "Following this, BAG-1 expression levels were shown as a limiting factor in the efficiency of breast cancer therapies." (PMID 37533517, 2022). "BAG-1 protein is one of the critical targets in breast cancer cells, which functions as a co-chaperone for HSP70/HSC70 proteins, triggers the cellular survival and results in a high proliferation rate compared to normal cells." (PMID 37533517, 2022). "BAG-1, a multifunctional apoptosis-controlling protein, has lately been related to an improved prognosis in patients with early-stage breast cancer." (PMID 35887080, 2022). "Despite the evidence about survival-related functional roles of Bag-1 in breast cancer, there has been limited data about its other cellular functions." (PMID 34995286, 2022). "Bag-1 has three different isoforms (Bag-1S, 33 kDa; Bag1M 46 kDa; and Bag-1L 52 kDA) that have distinct anti-apoptotic effects in breast cancer." (PMID 37533517, 2022). "This study aims to compare microRNA expression levels in wt and Bag-1 knockout (KO) MCF-7 breast cancer cells." (PMID 37533517, 2022). "All of these results highlighted that Bag-1 expression dependent alterations in MCF-7 breast cancer cells sharply changed the expression profile of cytoskeleton proteins, and affected EMT signalling." (PMID 34995286, 2022). "Considering the important roles of RTKs in breast cancer development, we investigated the effect of Bag-1 expression on the phosphorylation status of RTKs in MCF-7 cells by using Pathscan RTK Signaling Antibody Array kit." (PMID 34995286, 2022). "On the contrary, our previous studies showed that transient silencing of Bag-1 enhances paclitaxel or cisplatin-mediated apoptotic cell death in MCF-7 breast cancer cells." (PMID 34995286, 2022).
breast carcinoma (continued). "Stress-mediated Akt activation and reduced PTEN levels resulted in the reorganization of actin cytoskeleton and increased mesenchymal phenotype in Bag-1 KO MCF-7 breast cancer cells." (PMID 34995286, 2022). "In conclusion, the generation of CRISPR/Cas9 mediated Bag-1 KO MCF-7 breast cancer cells provides deeper understanding of the possible regulatory role of Bag-1 for Akt in cellular dynamics related to cytoskeleton organization." (PMID 34995286, 2022). "The multifunctional BAG-1 (Bcl-2 athanogene-1) protein promotes breast cancer survival through direct or indirect interaction partners." (PMID 37533517, 2022). "In this study, we aimed to generate a Bag-1 knockout (KO) MCF-7 breast cancer cell model using Clustered Regularly Interspaced Short Palindromic Repeats (CRISPR)/ CRISPR-associated 9 (Cas9) technique." (PMID 34995286, 2022). "Bag-1 was also found to prevent cellular ROS generation and stress-mediated growth inhibition in breast cancer cells." (PMID 34995286, 2022). "Considering the heterogeneity of breast cancer and the variability of BAG-1 -mediated cell response, it has become essential to determine microRNA (miRNA) functions in breast cancer depending on Bag-1 expression level." (PMID 37533517, 2022). "Small molecule inhibitors that disrupted Bag-1’s interactions at the C-terminal end were previously found to inhibit the growth of breast cancer cells." (PMID 34428256, 2021). "Our data suggested that Bag-1 indirectly forms a complex with Beclin 1 through at least one bridging molecule and improves autophagy and cell survival during starvation in breast cancer cell lines." (PMID 33561998, 2021). "Previous reports have demonstrated increased prevalence of BAG1 in breast cancer and clear-cell renal cell carcinoma 35-37, supporting our observation in this study." (PMID 34234849, 2021). "Bag-1 pull-down from cells and tissues from breast cancer patients validated these interactions and showed cancer-related prominence." (PMID 34428256, 2021). "To fill this gap, we here identified interactome of Bag-1 isoforms from MCF-7 breast cancer cells using tandem affinity purification (TAP) followed by mass spectrometry (MS)." (PMID 34428256, 2021). "In combination with other breast cancer chemotherapies, BAG1 down-regulation improved the effectiveness and cytotoxicity of the drugs in drug-resistant breast cancer cell lines." (PMID 34831344, 2021). "Pull-down experiments suggested a molecular interaction between Bag-1 and Beclin 1 in breast cancer cell lines." (PMID 33561998, 2021). "Dysregulation of BAG1 has been reported in many human cancers, including breast cancer, non-small cell lung cancer, glioblastoma, etc.." (PMID 33925460, 2021). "Co-immunoprecipitation assays from cell culture and tissues from breast cancer patients verified novel Bag-1 interactors including VCP/p97 and Rad23B." (PMID 34428256, 2021). "To investigate probable Bag-1/Beclin 1 interaction, we first performed His6-pull down experiments reciprocally in three different breast cancer cell lines, ranging from triple negative to triple positive." (PMID 33561998, 2021). "Silencing BAG1 in breast cancer cells increases resistance to tamoxifen and reduces apoptosis by activating the PI3K/Akt/mTOR signaling pathway, and the overexpression of ATG16L2 is related to poor prognosis in epithelial cancer." (PMID 32547955, 2020). "Overall, Bad inhibition by Bag-1 through activation of Raf and Akt kinases is an effective survival and growth strategy exploited by breast cancer cells." (PMID 31883527, 2019). "We investigated how the expression and phosphorylation of B-Raf, C-Raf, Akt and Bad changed upon Bag-1 overexpression and knockdown in breast epithelial and breast cancer cell lines." (PMID 31883527, 2019). "We found Bag-1 overexpression increased Bad phosphorylation at both residues, implicating both Raf and Akt kinases in Bag-1’s anti-apoptotic function in breast cancer cells." (PMID 31883527, 2019).
breast carcinoma (continued). "Bag-1 protects cells from a variety of apoptotic signals, and plays important roles in breast cancer development and chemoresistance." (PMID 31883527, 2019). "Ectopic expression of Bag-1 in breast cancer cell lines results in the activation of B-Raf, C-Raf and Akt kinases, which are also upregulated in breast tumors." (PMID 31883527, 2019). "Bag-1 forms complexes with B-Raf, C-Raf and Akt in breast cancer cells, enhancing their phosphorylation and activation, and ultimately leading to phosphorylation of the pro-apoptotic Bad protein at Ser112 and Ser136." (PMID 31883527, 2019). "In this study, we aimed to understand in more detail Bag-1’s pro-survival mechanism in breast cancer." (PMID 31883527, 2019). "Using immunoblot analysis, we examined Bag-1 expression profiles in tumor and normal tissues of breast cancer patients with different receptor status." (PMID 31883527, 2019). "To examine how Bag-1 expression was altered in each of these subtypes, we performed immunoblot analyses to detect Bag-1 levels in normal and tumor tissues from 30 breast cancer patients with different subtypes." (PMID 31883527, 2019). "Our findings supported the importance of Bag-1-mediated Akt and Raf activation and Bad inhibition in breast cancer etiology." (PMID 31883527, 2019). "Thirty-one articles that assessed the prognostic value of BAG-1 expression in breast cancer patients were considered eligible for inclusion in the systematic review." (PMID 28510570, 2017). "An inhibitor (Thio-2) that targets the BAG domain was shown to be efficacious in blocking the antiapoptotic action of Bag-1 in breast cancer and melanoma cells." (PMID 28826504, 2017). "In the same study, high levels of cytoplasmic or nuclear BAG-1 immunostaining were present in 9 of 14 (64%) and 7 of 14 (50%) ductal carcinoma in situ (a pre-invasive form of breast cancer) specimens, respectively." (PMID 28510570, 2017). "Treatment of patients with tumours exhibiting high nuclear BAG-1 expression with tamoxifen showed an improved outcome for local recurrence, distant metastases and breast cancer-specific death." (PMID 28510570, 2017). "Overall, the studies reported a high percentage of cells expressing BAG-1 within breast carcinomas, with five exhibiting positive staining for BAG-1 in >70% of tumours." (PMID 28510570, 2017). "After excluding reports that were out of the scope of our systematic review (articles had to report on the prognostic value of BAG-1 in breast cancer patients), 89 abstracts were reviewed and 58 that had used non-human samples were excluded." (PMID 28510570, 2017). "The co-chaperone protein Bcl-2-associated athanogene-1 (BAG-1) is overexpressed in breast cancer and has been incorporated in the oncotype DX and PAM50 breast cancer prognostic assays." (PMID 28510570, 2017). "A systematic review of published studies reporting BAG-1 (mRNA and/or protein) expression and clinical outcome in early breast cancer." (PMID 28510570, 2017). "Combining BAG-1- and HER2-targeted therapies synergistically inhibits HER2+ breast cancer cell growth, while interfering with BAG-1 function targets trastuzumab-resistant cells more effectively." (PMID 26958811, 2016). "Although the significance of BAG-1 as a biomarker in ER+ breast cancer is recognized, little is known about the role of BAG-1 in HER2+ disease." (PMID 26958811, 2016). "BAG-1 protein levels are increased in some HER2+ breast cancer cell lines, while HER2 gene transfer in MCF7 cells increases expression levels of BAG-1 and its interacting partner Bcl-2." (PMID 26958811, 2016).